PLCG2 (phospholipase C gamma 2)
Diseases named in the same sentence as PLCG2 in open-access papers (continued):
Sharing a sentence is not in itself a finding about the gene and the disease.
cancer (37 papers, 2012 to 2025). A tumor composed of atypical neoplastic, often pleomorphic cells that invade other tissues. "Unsurprisingly, dysregulation of PLCγ1 or PLCγ2 activity is associated with multiple maladies including immune disorders, cancers, and neurodegenerative diseases." (PMID 38551930, 2024). "In B cell leukemia patients treated with ibrutinib, the PLCγ2 activating Arg665Trp and Leu845Phe mutations frequently arise which cause cancer recurrence." (PMID 38551930, 2024). "Phospholipase Cγ2 (PLCG2) is a critical signaling molecule and associated with cancer, neurodegeneration and immune disorders." (PMID 37074454, 2023). "This population of cancer cells was characterized by the expression of PLCG2 and associated with a highly immunosuppressive TME." (PMID 37180110, 2023). "As a result, PLCγ2 dysfunction is associated with a variety of diseases including cancer, neurodegeneration, and immune disorders." (PMID 34157287, 2021). "Overall, these studies demonstrate that PLCγ2 is a driver or risk factor in a number of human cancers, both solid and hematological." (PMID 34157287, 2021). "We also characterize the effect of the PLCγ1 Arg687Trp mutation—homologous to the cancer therapy resistance Arg665Trp substitution in PLCγ2—on the characteristics of the tandem SH2 domain." (PMID 29972810, 2018). "PLCG2, a crucial enzyme in transmembrane signaling, has been implicated in breast and other cancers, yet its specific association with TNBC remains unclear." (PMID 40287845, 2025). "PLCG2 gene dysfunctions are associated with several pathologies, including neurodegenerative diseases, immune disorders (familial cold autoinflammatory syndrome three and antibody deficiencies), and cancer." (PMID 37509254, 2023). "Here, we review the signaling roles of PLCγ2 in hematopoietic cells to help understand the effect of mutations driving immune disorders and cancer and extrapolate from this to roles which may relate to protection against neurodegeneration." (PMID 34157287, 2021). "Furthermore, in tandem SH2 and γSA constructs, molecular dynamics and NMR results show that the Arg687Trp mutant in PLCγ1 (equivalent to the cancer mutation Arg665Trp in PLCγ2) perturbs the dynamic allosteric pathway." (PMID 29972810, 2018). "Our data suggest that DAPK3 inhibition could be an alternative to ibrutinib treatment in CLL, particularly in cases where resistance is associated with BTK/ PLCγ2 mutations, but also more generally in cancers characterised by DAPK1‐silencing, which is a common marker of poor prognosis." (PMID 32306542, 2020). "PLCG2 is a transmembrane signaling enzyme involved in inflammation, immunity-related diseases, and cancer." (PMID 39594421, 2024). "mRNA levels of PLCγ2 were more highly expressed in B-ALL than in most other human cancers (ranked 4 of 40)." (PMID 38811530, 2024). "The PLCG2 (Phospholipase C, gamma 2)-high cancer phenotype has stem-like, pro-metastatic features that contribute further to acquired therapeutic resistance." (PMID 38778348, 2024). "In this study, pan-cancer analysis showed that PLCG2 was highly expressed in a variety of cancers, especially in CRC cell lines, tissues, and organoids." (PMID 39494327, 2024). "For example, MAPK8IP2, ADAMTS12, and CHAF1B were upregulated in over five cancer types, while HHIP, PROX1, and PLCG2 were downregulated in over five cancer types." (PMID 35654793, 2022). "These disease situations highlight the potential to develop PLCγ2-modulating therapies that treat immune disease but must be tailored so as to avoid effects on other disease relevant processes such as cancer and neurodegeneration." (PMID 34157287, 2021). "Among the differentially expressed IRGs, we identified 5 IRGs (CD1B, XCL1, PLCG2, NGF, and OXTR) for inclusion in the risk score, and previous studies have indicated that these genes were related to immune processes and cancer progression." (PMID 32508884, 2020).
cancer (continued). "Therapeutics that selectively activate PLCγ1 and PLCγ2 could be useful in certain cancer and neurodegenerative indications as well." (PMID 38551930, 2024). "Previous studies have shown that PLCG2 was highly expressed in various malignant tumors." (PMID 39494327, 2024). "Recent studies have reported the integral role PLCG2 plays in developing malignant tumors." (PMID 39494327, 2024). "PLCG2 has an important role in malignant tumors, including hematological and solid tumors, and could affect tumorigenesis and progression through a variety of molecular mechanisms." (PMID 39494327, 2024). "The upregulated DEPs associated with pathways in cancer were IKBKB, AGT, and PLCG2." (PMID 35334492, 2022). "PLCG2 is involved in the proliferation and migration of many cancers." (PMID 35003085, 2021). "Thus, PLCG2 has a unique expression profile in malignant tumors." (PMID 39494327, 2024). "Interestingly, further GSEA analysis showed that the "PI3K-Akt signaling pathway", "T cell receptor signaling pathway", "mTOR signaling pathway" and "PD-L1 expression and PD-1 checkpoint pathway in cancer" were significantly activated in PLCG2 high-expression group." (PMID 39494327, 2024). "However, PLCγ2 was noted to be involved in Cisplatin resistance in another study of seven cancer cell lines, suggesting that the influence of PLCγ2 on tumorogenesis may be dependent on the cellular context." (PMID 34157287, 2021). "Overexpression of PLCG2 reduces LUAD cell proliferation and inhibits the growth of colorectal xenografts cancer in vivo." (PMID 39594421, 2024). "KEGG analysis identified adhesion, hematopoiesis and cancer-related proteoglycans as affected pathways (e.g. metformin: CD9, CTSL, IL5, HGF; insulin: EGF, EZR, PLCG2, TFRC)." (PMID 33690729, 2021). "Results from a GeneMANIA database analysis showed that PLCG2, CHI3L2, SH2D2A, and NLRP3 and 20 other proteins formed a complex network of which 12 genes were enriched in cancer-related pathways." (PMID 31993418, 2019). "PLCγ2 translocation is essential in transmitting TPA signal to PKCα and PKCα can directly promote the apoptosis of human cancer cell lines, thus, PLCγ2 is critical in the process of inducting apoptosis." (PMID 26096802, 2015). "Yet, data on the role of GSTM5, PDE6B, SGPP2, PDE1B, DGKB, and PLCG2 in cancer are still lacking." (PMID 33282950, 2020). "Our results suggested that PLCG2 can exist in eccDNA form and act as an oncogene that enhances mitochondrial respiration via ETC to promote the metastasis of NSCLC cells, which further illustrated that genes in the form of eccDNA may play a role in promoting cancer." (PMID 37031207, 2023). "We have recently shown that PL potently inhibits STAT3 activation in cancer cells and that STAT3 non-transcriptionally regulates collagen-induced platelet activation/aggregation by facilitating an interaction between the kinase Syk and the substrate PLCγ2." (PMID 26645674, 2015).
immune disorders (20 papers, 2012 to 2025). "Mutations in the gene cause the immune disorder PLCG2-associated antibody deficiency and immune dysregulation (PLAID) and its autoimmune version APLAID, which result in immunodeficiency." (PMID 38017562, 2023). "Hypermorphic mutations in PLCG2 in humans have been reported to cause autoinflammation and immune disorders, suggesting a key role for this enzyme in the regulation of immune cell function." (PMID 30711010, 2019). "Germline deletion and point mutations in PLCG2 cause complex immune disorders and autoinflammatory disease in humans." (PMID 30711010, 2019). "Studies in murine models and recent genetic studies of patients and their families have demonstrated a link between dominantly inherited complex immune disorders and gain-of-function mutations in PLCγ2." (PMID 23063561, 2012). "Other mutations in PLCG2 that lead to immune dysfunction are known to be activating." (PMID 30711010, 2019). "Several PLCγ2 mutations have been linked to inflammatory and auto-immune diseases." (PMID 30885223, 2019). "Furthermore, both PLCγ enzymes have also been implicated in aberrant cellular responses linked to disease development; one recent example is a link between dominantly inherited complex immune disorders and gain-of-function mutations in PLCγ2." (PMID 23063561, 2012). "Two other somatic PLCG2 variants detected in resistant CLL, p.Ser707Tyr and p.Asp993Gly, are also shared with immune disorders in APLAID and Ali5 mice, respectively." (PMID 32671674, 2020). "Some of these same mutations can also drive hematopoietic cell proliferation, for example, in Ibrutinib-refractory CLL, and so inhibition of PLCγ2 could be considered as a therapeutic modality in some malignancies and immune disorders." (PMID 34157287, 2021).
neurodegenerative disease (14 papers, 2018 to 2025). A disorder of the central nervous system characterized by gradual and progressive loss of neural tissue and neurologic function. "An issue with microglial genes was also raised in a study evaluating ABI family member 3 (ABI3) and phospholipase C gamma 2 (PLCG2) missense variants as neurodegenerative disease risk factors among Caucasians and African Americans." (PMID 40362170, 2025). "The previous discovery of AD-related mutations in the microglial expressed genes TREM2 and PLCγ2 has marked them as promising new targets to manipulate microglial function in neurodegenerative disease." (PMID 34615897, 2021). "However, such intervention would need to be approached with caution, as the constitutive roles of PLCγ2 are important, as are other gain-of-function variants that provide protection against neurodegenerative disease." (PMID 34157287, 2021). "Interestingly, the same PLCG2 variant associated with a lower risk for other neurodegenerative diseases and increased the likelihood for longevity." (PMID 32917267, 2020). "The role of PLCG2 in immune system signaling suggests it may also protect against other neurodegenerative diseases and possibly associates with longevity." (PMID 31131421, 2019). "This led us to question whether the rs72824905-G variant in PLCG2 is also associated with a reduced risk of other neurodegenerative diseases." (PMID 31131421, 2019). "Explaining the protective effect of the PLCγ2 protein on brain immune function may contribute to the design of successful therapeutic intervention strategies applicable to those at risk for neurodegenerative diseases." (PMID 31131421, 2019). "Together, these findings suggest a broad influence of PLCg2 activation in peripheral immunocompetent cells in multiple forms of neurodegenerative disease but most robustly in LBD." (PMID 39090623, 2024). "For example, next to the p.P522R variant in PLCG2 gene, the DRBI*04 variant in the HLA-gene, mainly expressed on antigen-presenting cells, also is associated with protection against neurodegenerative diseases." (PMID 37081539, 2023). "Activation of the CSF-1R/PLCγ2/ERK/Nrf2 pathway may be associated with inflammatory and neurodegenerative diseases." (PMID 40278547, 2025). "We saw that these genes of interest could be linked to known familial neurodegenerative disease genes (APP and HTT), and AD risk genes (APOE and PLCG2) from prior experimental studies using the Ingenuity database." (PMID 39231932, 2024). "We reasoned that next to AD, PLCG2-related immune signaling may be involved in the etiology of these other neurodegenerative diseases." (PMID 31131421, 2019). "Identification of association with disease status in other neurodegenerative diseases may aid in understanding the mechanism by which ABI3 and PLCG2 contribute to disease pathophysiology." (PMID 30326945, 2018). "These modules and clusters harbor known neurodegenerative disease genes including APOE, PLCG2, and BIN1." (PMID 35388616, 2022). "Although these findings require replication in larger cohorts, they suggest distinct effects of the microglial genes, ABI3 and PLCG2 in neurodegenerative diseases that harbor significant vs. low/no amyloid ß pathology." (PMID 30326945, 2018).
infection (8 papers, 2011 to 2025). The state of being infected such as from the introduction of a foreign agent such as serum, vaccine, antigenic substance or organism. "The alteration of PLCG2 expression by natural infection with SARS-CoV-2 has been discussed in the previous section." (PMID 36936955, 2023). "PLCG2 was reported to be activated after infection with attenuated M. tuberculosis strains regulating several functions of neutrophils such as generation of reactive oxygen intermediates (ROI) and induction of MAPK-signalling." (PMID 21629653, 2011). "In the aggregate, these studies suggest that variants in the CLEC7A/PLCG2/DUOX1/DUOXA1 pathway are not risk factors for primary infection but rather for control of infection (CLEC7A) and dissemination (PLCG2/DUOX1/DUOXA1)." (PMID 37233265, 2023). "Taken together, these data suggest variants in the CLEC7A/PLCG2/DUOX1/DUOXA1 pathway are not risk factors for primary infection but rather for control of infection (CLEC7A) and dissemination (PLCG2/DUOX1/DUOXA1)." (PMID 36166305, 2022). "Futhermore, it is reported that the lack of PLCγ2 impaired cytokine production in response to infection with C. albicans in PLCγ2-deficient macrophages." (PMID 30005593, 2018). "It is noteworthy that within our cohort, 26 patients with additional infections carried damaging variants in CLEC7A, PLCG2, or DUOX1/DUOXA1, compared with 6 of 27 patients without additional serious infections (n = 26 of 40 vs. 6 of 27; P = 0.001)." (PMID 36166305, 2022). "PLCγ2 can also be exploited by some intracellular bacteria, such as Ehrlichia chaffeensis in the monocytic THP-1 cell line, where the recruitment and activation of PLCγ2 is required to maintain stable calcium levels to facilitate intracellular infections." (PMID 34157287, 2021). "In this study, our findings showed that the lack of Dectin-1 impaired the phosphorylation of PLCγ2 in response to the infection with A. fumigatus, suggesting that Dectin-1 mediated the activation of PLCγ2 in the infected HCECs." (PMID 30005593, 2018).
neurological disease (4 papers, 2012 to 2022). "Taken together, various findings suggest that modulation of PLCγ2 signaling may be very promising for the development of AD and other neurological diseases." (PMID 36147734, 2022).
bacterial infection (2 papers, 2021 to 2022). "In addition to FcR signaling requiring PLCγ2 for efficient ROS production in murine neutrophils, PLCγ2 is also essential for postintegrin signaling induction of ROS, as well as being critical for the neutrophil-dependent host defense against bacterial infections in vivo." (PMID 34157287, 2021).
hematological malignancies (2 papers, 2021 to 2023). "The crucial nature of PLCγ2 in both the innate and adaptive immune system is further underscored by its vital roles in hematological malignancy." (PMID 34157287, 2021). "AVL-292, currently in phase 1 clinical trials for hematological malignancies, binds to BTK with high specificity and inhibits its activity, which subsequently impacts on PLCγ2 phosphorylation." (PMID 36612306, 2023).
PLCG2 also shares sentences with these, for which no sentence is quoted: familial cold autoinflammatory syndrome (4 papers); diffuse large B-cell lymphoma (3); familial Mediterranean fever (3); gastric cancer (3); acquired cold urticaria (2); AIDS (2); autoinflammatory syndrome (2); Blau syndrome (2); bronchiolitis (2); chronic granulomatous disease (2); common variable immunodeficiency (2); cryopyrin-associated periodic syndrome (2); enterocolitis (2); esophageal squamous cell carcinoma (2); follicular lymphoma (2); genetic disorder (2); inflammation (2); mild cognitive impairment (2); acute lymphoblastic leukemia (1); adenoma (1); Aicardi-Goutières syndrome (1); and retinal (1); anemia (1); angina pectoris (1); angioedema (1); angiosarcoma (1); ankylosing spondylitis (1); autosomal dominant disease (1); B-cell lymphopenia (1); bladder NECs (1).
A further 58 diseases each share a sentence with PLCG2 in 1 paper.